DDR1 (discoidin domain receptor tyrosine kinase 1)
Diseases named in the same sentence as DDR1 in open-access papers (continued):
Sharing a sentence is not in itself a finding about the gene and the disease.
gastric cancer (continued). "In the present study, we investigated the infiltration situation based on DDR1 in gastric cancer." (PMID 35935941, 2022). "Gastric cancer exhibited significantly increased DDR1 expression compared to normal tissues." (PMID 35935941, 2022). "Inhibition of DDR1 may have the potential to alleviate the strong invasiveness and metastasis of advanced gastric cancer." (PMID 35935941, 2022). "Furthermore, we interrogated DDR1 expression in 37 gastric cancer cell lines using the GEDS platform." (PMID 35935941, 2022). "Consequently, we studied data from multiple databases to understand the effect of DDR1 in gastric cancer." (PMID 35935941, 2022). "These suggests that inhibition of DDR1 may be beneficial for the treatment of advanced gastric cancer." (PMID 35935941, 2022). "Our analysis revealed that the expression of DDR1 was upregulated in gastric cancer." (PMID 35935941, 2022). "Finally, the effect of DDR1 expression in gastric cancer on immune cell infiltration was investigated through TIMER database." (PMID 35935941, 2022). "Moreover, studies based on gender, tumor–node–metastasis (TNM) stages, Lauren classification, and other clinicopathological characteristics also proved the clinical prognostic value of DDR1 in the treatment of gastric cancer." (PMID 35935941, 2022). "Notably, high expression of DDR1 in N2 and M1 stages of gastric cancer had comparatively high HR values in the prognostic analysis, revealing the crucial role of DDR1 in local lymph node metastasis and distant metastasis of gastric cancer." (PMID 35935941, 2022). "For example, inhibition of DDR1 in a subcutaneous gastric cancer xenograft slows tumor growth." (PMID 33917302, 2021). "Our study demonstrated the potential of DDR1 as a new prognostic marker of gastric cancers." (PMID 28143619, 2017). "Based on the results of the present study, a novel inhibitor of DDR1, 7rh benzamide, is potentially efficacious in preventing tumor recurrence after curative resection in DDR1-expressing gastric cancer through the suppression of cancer cell migration and tumorigenic abilities." (PMID 28143619, 2017). "Prior to this study, the expression of DDR1 was unexplored in gastric cancers." (PMID 28143619, 2017). "Therefore, we suggest that DDR1 has good prognostic value as a potential tumor therapeutic target in patients with gastric cancer, thereby effectively promoting the development of precision therapy for gastric cancer." (PMID 35935941, 2022). "Since we have noticed the significant impact of DDR1 expression on the prognosis of gastric cancer patients, the prognostic value of DDR1 was further evaluated according to various clinicopathological characteristics of gastric cancer by virtue of the Kaplan–Meier plotter database." (PMID 35935941, 2022). "Jiang and colleagues demonstrated that the miR-221-5p expression was suppressed in gastric cancer tissues, overexpression of miR-221-5p reduced cisplatin chemoresistance of gastric tumor cells, and suppressed cell proliferation and migration via suppressing DDR1." (PMID 35371339, 2022). "However, the significance of DDR1 expression in gastric cancers is yet to be evaluated." (PMID 28143619, 2017). "However, the clinical relevance of DDR1 expression in gastric carcinoma is yet to be investigated." (PMID 28143619, 2017). "Importantly, inhibition of DDR1 is an attractive strategy for gastric carcinoma therapy." (PMID 28143619, 2017). "This article demonstrates that DDR1, a primary member of extracellular matrix (ECM) receptors, is the key driver for gastric cancer (GC) progression, providing new insights into ECM‐cells interaction in tumor progression." (PMID 39024501, 2024). "Thus, as described in our study, DDR1 might be a potential target for gastric cancer." (PMID 35935941, 2022).
gastric cancer (continued). "It turned out that the high expression of DDR1 closely related to poor prognosis of both female (OS HR = 1.74, p = 0.002) and male (OS HR = 1.29, p = 0.021; PPS HR = 1.49, p = 0.0026) gastric cancer patients." (PMID 35935941, 2022). "Overexpression of miR-221-5p in gastric cancer cells inhibits not only EMT, but also proliferation and invasion through modulation of DDR1 expression." (PMID 33917302, 2021). "DDR1 is not expressed in normal gastric epithelial cells, but it is expressed in half of gastric carcinoma, showing that DDR1 is an important mediator of gastric cancer aggressiveness." (PMID 33917302, 2021). "DDR1 and DDR2 were found to be significantly overexpressed in gastric cancer (GC) cell lines compared to normal gastric mucosal cells, particularly in poorly differentiated GC cells." (PMID 37007062, 2023). "In addition, even though there is a significant and negative correlation between DDR1 and many immune markers of various TIICs in gastric cancer, the correlation is not very strong, which also reflects the complexity of the mechanism of immune infiltration." (PMID 35935941, 2022). "Therefore, the elevated expression of DDR1, which uses the stromal collagen as a ligand, might be a novel target for gastric cancer treatment." (PMID 28143619, 2017).
lung adenocarcinoma (16 papers, 2017 to 2026). A carcinoma that arises from the lung and is characterized by the presence of malignant glandular epithelial cells. "We observed that compared to normal tissues, the expression level of DDR1 is significantly upregulated in Lung Adenocarcinoma (LUAD), Lung Squamous Cell Carcinoma (LUSC) and Diffused Large B Cell Lymphoma (DLBCL)." (PMID 40713963, 2025). "Through binding and activating the AKT signaling pathway, DDR1 promotes the migratory and invasive capabilities of lung adenocarcinoma cells." (PMID 40563472, 2025). "Two human lung adenocarcinoma cell lines, A549 and Calu-3, were treated with collagen type I and transfected with DDR1 siRNA." (PMID 38308500, 2024). "In the current study, we investigated the effect of DDR1 on t-DARPP expression in lung adenocarcinoma." (PMID 38308500, 2024). "In a lung adenocarcinoma KRAS-mutated PDX model, dual inhibition of DDR1 and NOTCH signaling was found to induce tumor regression." (PMID 36911198, 2023). "We found that pharmacological inhibition and knockout of DDR1 increased the tumor burden in an immunocompetent mouse model of lung adenocarcinoma." (PMID 38136314, 2023). "This work aimed to explore the impact of DDR1 expression on immune cell infiltration in lung adenocarcinoma." (PMID 38136314, 2023). "Regulatory T cells, which promote tumorigenesis by suppressing the immune system, were also more common among The Cancer Genome Atlas (TCGA) lung adenocarcinoma patients with low DDR1 expression." (PMID 38136314, 2023). "The changes in Tregs with DDR1 knockout were also observed in the TCGA gene expression dataset on lung adenocarcinoma patients." (PMID 38136314, 2023). "One confirmed homing mechanism used by lung adenocarcinoma cells is discoidin domain receptor 1 (DDR1)." (PMID 33262947, 2020). "Furthermore, in KRAS-mutant lung adenocarcinoma, combined inhibition of DDR1 and Notch signaling resulted in regression of patient-derived xenografts with an efficacy comparable to standard chemotherapy." (PMID 32211044, 2020). "DDR1 is involved in the formation and progression of KRAS-mutant lung adenocarcinoma, particularly in early stages, and its upregulation acts as a compensatory mechanism in KRAS-knockdown cancer cells." (PMID 40563472, 2025). "Independent groups have reported DDR1 as a potential therapeutic candidate in KRAS-driven tumors, and combinatorial targeting of DDR1 has also been shown to be efficacious in KRAS-mutant tumors, lung adenocarcinoma, and recently pancreatic adenocarcinoma." (PMID 35664781, 2022).
leukemia (12 papers, 2015 to 2024). A malignant (clonal) hematologic disorder, involving hematopoietic stem cells and characterized by the presence of primitive or atypical myeloid or lymphoid cells in the bone marrow and the blood. "In particular, we focused our attention on its potential effect on CCL17, CD40 and PI3KCD mRNAs, which are biologically relevant to CLL, and on DDR1 mRNA that encodes a tyrosine kinase receptor expressed in several tumors and leukemias." (PMID 26305332, 2015). "Nilotinib is a tyrosine kinase inhibitor that is FDA-approved for leukemia and potently inhibits DDR-1." (PMID 37194065, 2023). "FDA-approved drugs that inhibit ABL1/2 and DDR1 have been used for decades to treat leukemia." (PMID 36765910, 2023). "Nilotinib is a selective inhibitor of DDR1 activation, which has been approved by FDA of USA as an anti-leukemia drug." (PMID 38388466, 2024). "When comparing the targets between Dasatinib and imatinib/nilotinib, there are six common target kinases: Kit, PDGFR, ABL1, DDR1, ARG (ABL2), and the fusion kinase present only in certain leukemias, BCR-Abl." (PMID 36338985, 2022). "This unexpected result raises the possibility that DDR1 phosphorylates BCR also in CML and that BCR role in human cancer may not be restricted to leukaemia." (PMID 29438985, 2018).
atherosclerosis (11 papers, 2007 to 2024). A disease characterized by the build-up of fatty material and calcium deposition in the arterial wall resulting in partial or complete occlusion of the arterial lumen. "Discoidin domain receptor 1 (DDR1) is a collagen binding receptor tyrosine kinase implicated in atherosclerosis, fibrosis, and cancer." (PMID 32360427, 2020). "Discoidin domain receptor 1 (DDR1) is a collagen-activated receptor tyrosine kinase extensively implicated in diseases such as cancer, atherosclerosis and fibrosis." (PMID 29859097, 2018). "In animal models of atherosclerosis, DDR1 null mice showed a reduction in atherosclerotic lesions, which was associated with a pro-inflammatory effect of DDR1 by promoting macrophage infiltration." (PMID 28536691, 2017). "The tyrosine kinase discoidin domain receptor 1 (DDR1) is critical for normal embryonic development and organogenesis and is also associated with the advancement of several diseases, such as different types of cancer, atherosclerosis, and fibrotic illnesses." (PMID 39507419, 2024). "The discoidin domain receptor 1 (DDR1) tyrosine kinase is fundamental for proper embryonic development and organogenesis and also implicated in the progression of several diseases including various cancers, atherosclerosis and fibrotic diseases." (PMID 37833282, 2023). "However, DDR1 expression and function are also strongly linked to fibrotic disorders such as atherosclerosis, arthritis, and several types of cancer." (PMID 32664526, 2020). "In this study, we show that DDR1 acts as a direct mechanosensor in ECs, regulating the cellular responses to shear flow and hence the site-specific distribution of atherosclerosis." (PMID 37833282, 2023). "Taken together, these results indicate that endothelial DDR1 is required for the endothelial responses to fluid shear stress and the site-specific distribution of atherosclerosis." (PMID 37833282, 2023). "It is pertinent to note that previous studies on DDRs in relation to collagen remodeling during vascular injury and progression of atherosclerosis were focused largely on DDR1." (PMID 31805124, 2019). "Discoidin domain receptor 1 (DDR1) is a collagen-activated receptor tyrosine kinase (RTK) extensively implicated in diseases such as cancer, atherosclerosis and fibrosis." (PMID 29859097, 2018). "Deregulated function of DDR1 has been described in various human diseases, including several types of cancer, atherosclerosis, osteoarthritis, and fibrotic diseases." (PMID 28536691, 2017). "For example, DDR1 is believed to play a role in atherosclerosis, and is mainly targeted by dasatinib and nilotinib, and perhaps by imatinib as well." (PMID 33530148, 2015). "Excessive signaling by DDR1 and DDR2 has been linked to the progression of various human diseases, including fibrosis, atherosclerosis and cancer." (PMID 24768818, 2014). "DDR1 has been seen to act as a direct mechanosensor in endothelial cells, which governs the cellular responsiveness toward shear flow and consequently the site-specific distribution of atherosclerosis." (PMID 39507419, 2024). "However, our study is the first to report the role of DDR1 in regulating endothelial responses to fluid shear stress and the resulting atherosclerosis." (PMID 37833282, 2023). "Our findings establish a previously uncharacterized role of DDR1 in directly sensing flow, propose a conceptual framework for understanding upstream regulation of the YAP signaling, and offer a mechanism by which endothelial activation of DDR1 promotes atherosclerosis." (PMID 37833282, 2023). "To investigate the biological significance of our findings, we generated the inducible EC-specific Ddr1 knockout mice Ddr1iECKO (Ddr1flox/flox, Cdh5-CreERT2+) and employed the mice to test the role of endothelial DDR1 in disturbed flow-accelerated vascular inflammation and atherosclerosis." (PMID 37833282, 2023).
atherosclerosis (continued). "DDR1 attenuates inflammation in models of atherosclerosis we previously showed that vascularization could facilitate transport across the BBB and result in a beneficial long-term immune response and potential clinical stabilization." (PMID 36557263, 2022). "Previous work from our laboratory established an important role for DDR1 in atherosclerosis." (PMID 32360427, 2020). "We have used a diet-induced mouse model of atherosclerosis, metabolic disease and obesity to determine whether DDR1 deletion impacts upon adipose tissue remodeling and metabolic dysfunction." (PMID 32360427, 2020). "The collagen-binding RTKs, DDR1 and DDR2, have previously been linked to various human diseases including fibrosis, atherosclerosis, and cancer." (PMID 17299390, 2007).
bladder cancer (11 papers, 2019 to 2025). "Expression of DDR1 is described on different epithelial cells; its overexpression in bladder cancer was associated with poor outcomes." (PMID 37626918, 2023). "The cell viability (OD values) of erastin‐induced bladder cancer cells after being transfected with si‐DDR1 or OE‐DDR1." (PMID 40105492, 2025). "Inhibition of STAT3 by Napabucasin, a Phase II/III FDA-approved drug, significantly abrogated the capacity of DDR1-expressing cancer cells to form lung metastases from bladder cancer." (PMID 38907027, 2024). "A high DDR1 expression in bladder cancer was also found to be correlated with poor prognosis of bladder cancer." (PMID 37627900, 2023). "The overexpression of DDR1 promotes the cell invasion of bladder cancer in vitro and tumor xenograft growth in vivo, whereas the knockdown of DDR1 yielded the opposite effect." (PMID 37627900, 2023). "In bladder cancer, migration and anchorage-independent growth are dependent on DDR1/IGF-1R or DDR1/IR-A crosstalk." (PMID 33917302, 2021). "More recent data have demonstrated that DDR1 is upregulated in bladder cancer tissues and cell lines, where it functionally interacts with both the IGF1R and the IR and modulates ligand-evoked bladder cancer cell motility." (PMID 33673232, 2021). "In a cohort of patients with advanced bladder cancer receiving immunotherapy, we were also able to divide the patients into two molecular subclasses: DDR1 patients with low expression of DDR-related genes and DDR2 patients with high expression of DDR-related genes." (PMID 34335575, 2021). "Therefore, DDR1 may represent a novel biomarker for bladder cancer." (PMID 33543032, 2020). "This physical interaction results in cross-talk among DDR1, IGF-IR, and insulin receptor A (IR-A) for bladder cancer progression." (PMID 33543032, 2020). "Both treatment conditions enhanced phospho-tyrosine Stat3 level in the T24 bladder cancer and the human PDX model, which was significantly diminished by a CD167a/DDR1 selective kinase inhibitor (DDR1-IN-1)." (PMID 31086186, 2019).
glioblastoma (10 papers, 2019 to 2026). The most malignant astrocytic tumor (WHO grade IV). "DDR1, which is a type of cell adhesion molecule, causes radioresistance in glioblastoma stem-like and bulk cells by its adherence to the extracellular matrix and after modulation of autophagy/macroautophagy." (PMID 33525678, 2021). "DDR1-IN-1 was previously shown to induce autophagic cell death and to increase radiochemosensitivity in glioblastoma." (PMID 40025071, 2025). "The AV/PI staining further revealed an increased PI + /AV− cell population in MCF-7 cells as a response to DDR1-IN-1 treatment, a similar phenomenon was also noticed in glioblastoma U-87 cell line." (PMID 40025071, 2025). "DDR1 promoted development in orthotopic glioblastoma mouse models and human ER-positive, HER2-negative breast cancer and reduced the efficacy of chemotherapy agents by activating the AKT signaling pathway in these tumor cells." (PMID 37031216, 2023). "A previous report has revealed that DDR1 interacts with the 14-3-3/Beclin1/Akt1 protein complex and regulates autophagy-mediated therapy sensitivity in glioblastoma through phosphorylation of the tyrosine 513 site." (PMID 38071340, 2023). "It has been reported that DDR1 inhibition sensitizes glioblastoma cells to radiotherapy by inducing autophagy." (PMID 33824475, 2021). "DDR1-IN-1 induces autophagic cell death in glioblastoma cells." (PMID 40025071, 2025). "DDR1-IN-1 combined with radiochemotherapy increases glioblastoma cell sensitivity to therapy." (PMID 40603853, 2025). "Silencing of DDR1 reduces the radioresistance of glioblastoma cells via inducing autophagy." (PMID 33525678, 2021). "Consequently, targeting DDR1 might be a novel approach for sensitizing glioblastoma cells to radiation treatment." (PMID 33525678, 2021).
triple-negative breast carcinoma (10 papers, 2020 to 2025). An invasive breast carcinoma which is negative for expression of estrogen receptor (ER), progesterone receptor (PR), and human epidermal growth factor receptor 2 (HER2). "The results showed that similar to the effects of RUNX1 expression in luminal cancers, elevated expression of DDR1 associated with increased survival in non-triple negative breast cancers (ER+/PR+/HER2+) (Figures 6Ci and 6Cii)." (PMID 40614729, 2025). "A recent study that looked at the role of DDR1 in triple-negative breast cancer showed that DDR1 inhibits the infiltration of anti-tumor immune cells by promoting collagen fibers alignment." (PMID 36249782, 2022). "In the triple-negative breast cancer subtype (TNBC, or basal breast cancer) dysregulation of both DDR1 and DDR2 has been associated with increased invasion, and a poorer prognosis." (PMID 34805157, 2021). "Our data also echoed the study linking DDR1 to T cell exclusion in triple-negative breast cancer, although their proposed mechanism suggested that the extracellular domain of DDR1, rather than its intracellular kinase domain, aligned collagen fibers and then impeded immune infiltration." (PMID 40993737, 2025). "In head and neck squamous cell carcinoma (HNSCC) and triple-negative breast cancer (TNBC), type III collagen stimulates DDR1 phosphorylation, activating STAT1 to maintain tumor dormancy." (PMID 40563472, 2025). "In triple-negative breast cancer (TNBC), DDR1 promotes tumor cell proliferation." (PMID 40563472, 2025). "Furthermore, in triple negative breast cancer, H-Ras promotes EMT by downregulation of DDR1 expression via its transcriptional repressor of ZEB1." (PMID 34805157, 2021).